HDGF (heparin binding growth factor)
Diseases named in the same sentence as HDGF in open-access papers (continued):
Sharing a sentence is not in itself a finding about the gene and the disease.
cancer (continued). "In our study, we found that HDGF expression was higher in cancer tissues than in adjacent noncancerous tissues." (PMID 30004626, 2018). "Serum HDGF concentration has been reported to serve as a negative prognostic marker for cancer." (PMID 40770862, 2025). "Second, different proteoforms from the same cancer-related gene (e.g., DAP, CALM1, HDGF, JPT1, RALY, and NPM1) may have potentially varied biological functions in modulating CRC metastasis, because they show opposite expression profiles between the SW480 and SW620 cells." (PMID 36542699, 2022). "However, the abundance of nuclear-localized HDGF is considered a remarkable prognostic factor in various cancers, but its function in cancer has never been identified." (PMID 34106558, 2021). "The dramatically negative impact of HDGF on survival has been reported in various cancers." (PMID 26296979, 2015). "Here, we found that G3BP2 was protected by LINC01554 from ubiquitin-mediated protein degradation and stabilized HDGF mRNA transcripts to drive ESCC metastasis, which has not yet been reported during cancer progression." (PMID 34782720, 2022). "Besides, the roles of seven genes (NR1D2, TANK, LRSAM1, PLXNA1, INHBE, HDGF, and ARAF) in SCLC have not been reported, however those genes have been reported to play a vital role in other type cancer." (PMID 34741430, 2021).
infection (5 papers, 2013 to 2023). The state of being infected such as from the introduction of a foreign agent such as serum, vaccine, antigenic substance or organism. "Especially, the expression level of HDGF (hepatoma-derived growth factor; ENSG00000143321.14) was significantly decreased under the replication-deficient conditions; notably, HDGF expression started to decrease even during the early phase of infection in the 293 cells." (PMID 25275311, 2014). "We found different signaling of cytotoxicity and invasion of human gastric organoids in response to HDGF and TNFα during infection by H. pylori." (PMID 37047540, 2023). "A notable increase in HDGF protein level was observed in AGS cells with HP49503 infection, using immunoblotting and immunofluorescence staining assays." (PMID 30513684, 2018). "Our results showed that the upregulation of HDGF, compared with the steady-state level, was observed after infection with VA-deleted AdVs both during the early phase of the replicating condition and during replication-deficient conditions." (PMID 25275311, 2014). "The results showed that the transcript levels of HDGF started to decrease at 8 h after infection (early phase) in FG AdV-infected cells (white circle)." (PMID 25275311, 2014). "Since AraC amplifies the effect during the early phase, this result confirmed that HDGF gene expression is induced during the early phase of infection." (PMID 25275311, 2014). "HP49503 infection significantly induced HDGF mRNA expression." (PMID 30513684, 2018). "Furthermore, the results from ELISA assay revealed that HP49503 infection could induce higher concentration of secreted HDGF form human AGS cells." (PMID 30513684, 2018). "In the case of infection by H. pylori ATCC 40593, recombinant HDGF at high dose (100 ng/mL) increased the cell viability of 3-D organoids." (PMID 37047540, 2023).
GI tumors (1 paper, 2024). "In addition, some transcription factors, including HDGF, NCL, PCBP1, and PCBP2, were also found to be largely modified by lysine lactylation in all four types of GI tumors, and further confirming the regulation of Kla in gene expression." (PMID 39018247, 2024).
gynecological tumors (1 paper, 2023). "Several factors like SDF-1 alpha (as occurs in gynecological tumors), HDGF (hepatoma-derived growth factor), VEGF, bFGF, or MCP-1 (monocyte chemotactic protein-1) are also involved in the proliferation of different cell types." (PMID 38004925, 2023).
kidney diseases (1 paper, 2020). "Midkine (MDK), a heparin-binding growth factor cytokine, is involved in the pathogenesis of kidney diseases by augmenting leukocyte trafficking and activation." (PMID 32879333, 2020).
neurological disease (1 paper, 2023). "However, overexpression of HDGF was not sufficient to significantly improve neurological disease phenotypes." (PMID 37580082, 2023).
HDGF also shares sentences with these, for which no sentence is quoted: gastrointestinal stromal tumor (5 papers); osteosarcoma (3); esophageal squamous cell carcinoma (2); retinoblastoma (2); acute myeloid leukemia (1); aging (1); breast tumor (1); cardiac hypertrophy (1); cholangiocarcinoma (1); gynecological cancer (1); ischaemic heart diseases (1); liver disease (1); metastasis (1); metastatic melanoma (1); oral squamous cell carcinoma (1); rectal tumor (1); Sepsis (1); squamous intraepithelial lesions (1); Stroke (1); tongue squamous cell carcinoma (1).